ACAP2 (ArfGAP with coiled-coil, ankyrin repeat and PH domains 2)
Description:
GTPase-activating protein (GAP) for ADP ribosylation factor 6 (ARF6). Doesn't show GAP activity for RAB35.
Synonyms: Cnt-b2; CENTB2; KIAA0041
Tractability: Small molecule: a structure with a bound ligand is known. Antibody: UniProt places it where antibodies can reach, with high confidence; its Gene Ontology location is reachable by antibodies, with high confidence. PROTAC: ubiquitination databases record sites on it; its protein half-life has been measured.
Gene: Protein-coding gene on chromosome 3 (195,274,738 to 195,443,091, reverse strand). Ensembl gene ENSG00000114331.
Subcellular location: Cell membrane; Endosome membrane
Subcellular location (Human Protein Atlas): Endosomes
Gene Ontology:
Molecular function: GTPase activator activity; protein binding; phosphatidylinositol-3,5-bisphosphate binding; small GTPase binding
Biological process: actin filament-based process; actin cytoskeleton organization; cellular response to nerve growth factor stimulus; endocytic recycling
Cellular component: membrane; plasma membrane; ruffle; endosome membrane; cytoplasm
Genetic constraint (gnomAD): Loss-of-function variants: 26 observed, 76.77 expected, observed/expected ratio (o/e) 0.34, 90% interval 0.25 to 0.47. The upper end of that interval is the gene's LOEUF score, 0.47, which puts it in group 2 of 6, group 1 being the genes least tolerant of losing a copy. Missense variants: 486 observed, 711.48 expected, observed/expected ratio (o/e) 0.68, 90% interval 0.63 to 0.74. Synonymous variants: 217 observed, 250.86 expected, observed/expected ratio (o/e) 0.87, 90% interval 0.77 to 0.97.
Homologues: Orthologues: chimpanzee ACAP2 (100% identical), rabbit ACAP2 (98% identical), guinea pig ACAP2 (98% identical), dog ACAP2 (97% identical), pig ACAP2 (96% identical), macaque ACAP2 (96% identical), mouse Acap2 (95% identical), rat Acap2 (95% identical), tropical clawed frog acap2 (81% identical), zebrafish acap2b (72% identical), zebrafish acap2a (68% identical). Paralogues in human: ACAP3 (61% identical), ACAP1 (51% identical), ASAP2 (26% identical), ASAP1 (24% identical), ASAP3 (24% identical), AGAP1 (19% identical), ARAP2 (19% identical), AGAP3 (19% identical), AGAP2 (18% identical), ARAP1 (17% identical), ARAP3 (17% identical), AGAP5 (16% identical), and 16 more.
Diseases named in the same sentence as ACAP2 in open-access papers:
ACAP2 is named in the same sentence as 19 diseases in open-access papers, as found by Europe PMC text mining. Sharing a sentence is not in itself a finding about the gene and the disease. The quoted sentences say what the papers report.
esophageal cancer (4 papers, 2021 to 2022). A primary or metastatic malignant neoplasm involving the esophagus. "Research showed knockdown of ACAP2 blocks apoptosis in cancer cells in response to the chemotherapeutic antimetabolite 5-fluorouracil and ACAP2 expression was down-regulated in some esophageal cancers, leukemias and lymphomas." (PMID 36506317, 2022). "We also found that the expression levels of ACAP2 were significantly downregulated in some esophageal cancers, and a similar trend was observed in both leukemias and lymphomas based on the analysis of the Oncomine database." (PMID 34671193, 2021).
Esotropia (1 paper, 2024). A form of strabismus with one or both eyes turned inward ('crossed') to a relatively severe degree, usually defined as 10 diopters or more. "Additionally, in a GWAS with BBJ (180K), ACAP2 in chromosome 3 and HLA-F in chromosome 6 were suggested as candidates in the combined group of esotropia and exotropia." (PMID 39000095, 2024).
lung carcinoma (1 paper, 2024). "Secondly, three genes [ArfGAP With Coiled-Coil, Ankyrin Repeat And PH Domains 2 (ACAP2), Enolase3 (ENO3), and prostate stem cell antigen (PSCA)] showed an upregulation in lung cancer tissue, suggesting their role as an oncogene." (PMID 39199663, 2024).
tumor (6 papers, 2013 to 2022). "The results show that the decrease in ACAP2 mRNA level caused by siACAP2 can reduce the expression of ACAP2 protein in cells and significantly promote tumor proliferation, migration and invasion." (PMID 34671193, 2021). "Further target gene analysis confirmed ACAP2 was a target gene regulated by miR-3656 and exhibited a negative regulatory effect on tumor proliferation." (PMID 34671193, 2021). "Through bioinformatics analysis, we found that hsa_circ-ACAP2 is upregulated in many types of tumor tissues." (PMID 33363013, 2020). "Of note, we identified newly emerged 8 non-synonymous somatic mutations of the genes (ACAP2, CARD10, KIAA0556, PAAQR7, PPP1R39, SAFB2, STARD9, and ZFYVE9) in the imatinib-resistant tumor tissue." (PMID 23922791, 2013). "Higher mRNA levels of ACAP2, ECHDC3, EGR1, and CD74 were highly associated with tumor development." (PMID 35999505, 2022). "In addition, current reports suggest that ACAP2 helps the formation of tumor-promoting exosomes." (PMID 34671193, 2021). "To test this hypothesis, we first determined the relationship between changes in ACAP2 expression and tumor development in the absence of miR-3656 by transfecting equivalent siACAP2 siRNA into ESCC cells." (PMID 34671193, 2021).
ACAP2 also shares sentences with these, for which no sentence is quoted: cancer (6 papers); leukemia (4); lymphoma (4); colon cancer (2); myocardial infarction (2); breast carcinoma (1); esophageal squamous cell carcinoma (1); Exotropia (1); head and neck squamous cell carcinoma (1); hypertrophic cardiomyopathy (1); malignant melanoma (1); neuroblastoma (1); ovarian carcinoma (1); papillary thyroid cancer (1); renal carcinoma (1).